INS (insulin)
Diseases named in the same sentence as INS in open-access papers (continued):
Sharing a sentence is not in itself a finding about the gene and the disease.
Insulin resistance (continued). "Oral administration of BAIBA for 4 weeks reduced blood glucose and lipids levels, hepatic key enzymes of gluconeogenesis and lipogenesis expressions, attenuated hepatic insulin resistance and lipid accumulation, and improved insulin signaling in type 2 diabetic mice." (PMID 26907958, 2016). "Our insulin tolerance tests suggest that Aox4−/− animals show signs of mild insulin resistance." (PMID 27456060, 2016). "To organize discussion of this topic, we differentiate between primary mechanisms of insulin resistance – due to impaired insulin-to-insulin-receptor signaling – and secondary mechanisms of insulin resistance, such as impaired glucose uptake or inappropriately elevated glucose production." (PMID 27053133, 2016). "Resveratrol dampened the effect on the LPS-induced hyperinsulinemia and specifically reduced inflammation in epididymal adipose tissue pointing towards a possible important involvement of this tissue for the effects on insulin resistance and insulin secretion as a result of metabolic endotoxemia." (PMID 26751381, 2016). "Insulin resistance refers to decreased capability of insulin to promote glucose uptake." (PMID 28101517, 2016). "The adipocyte hypertrophy seen in K14-VEGF-C mice could lead to a reduction in adipocyte insulin sensitivity, which in turn could promote ectopic lipid accumulation in the liver and evoke insulin resistance in this model." (PMID 27511834, 2016). "Here, we tested the hypothesis that central IGF‐1 is uniquely capable of restoring whole‐body insulin action in a model of age‐related insulin resistance and declining IGF‐1 levels." (PMID 26534869, 2016). "The fatty liver might, through these mechanisms, influence both key pathomechanisms of prediabetes, namely insulin resistance and inability to produce compensatory insulin hypersecretion." (PMID 27344314, 2016). "As expected, HF feeding increased fasting bood glucose and insulin levels, as well as elevated the index of insulin resistance and impaired glucose tolerance compared with LF feeding, indicating that metabolic aberrations related to impaired glucose tolerance existed in HF-fed control mice." (PMID 26731528, 2016). "The abundance of proinflammatory cytokines and chemokines in adipose tissue is a key contributor to insulin resistance in type 2 diabetes, and blocking of inflammatory signaling pathways or immune cell infiltration in adipose tissue improves insulin sensitivity." (PMID 27110066, 2016). "Further, it was reported that a loss-of-function mutation in ABCA1 reduced insulin secretory capacity without affecting insulin resistance in humans." (PMID 26881755, 2016). "Therefore, HUA inhibited insulin-induced glucose uptake and induced insulin resistance in H9c2 cardiomyocytes." (PMID 26836389, 2016). "In this study, dutasteride treatment was associated with hepatic insulin resistance, hepatic lipid accumulation, and decreased adipose lipid mobilization without impacting peripheral insulin sensitivity." (PMID 26574953, 2016). "It has been hypothesized that in a state of peripheral insulin-resistance, insulin may cross the blood brain barrier and stimulate the overproduction of proinflammatory cytokines." (PMID 26432692, 2016). "This is consistent with previous studies revealing that triglycerides and FFAs could induce insulin resistance by impairing insulin signaling in muscle and liver." (PMID 27357657, 2016). "Suppression of vascular insulin signaling by PM2.5 may accelerate the progression to systemic insulin resistance, particularly in the context of diet-induced obesity." (PMID 27128347, 2016). "Similarly, in CD, chronic hypercortisolism blocks the binding of insulin to peripheral tissues, resulting in insulin resistance, and inhibits the release of insulin by pancreatic beta cells." (PMID 27405306, 2016). "Amino acid supplementation in humans directly promotes insulin resistance, and may be related to effects on insulin signaling in skeletal muscle." (PMID 26863521, 2016).
Insulin resistance (continued). "Moreover, adiponectin plays a protective role in insulin resistance and adiponectin induces insulin secretion." (PMID 27598258, 2016). "Lowered insulin sensitivity may lead to insulin resistance, which in turn leads to elevated levels of serum glucose and eventually to type 2 diabetes." (PMID 28123923, 2016). "Overall, we conclude that at this early stage of development of metabolic disorder, subordinate mice manifest molecular signatures of insulin resistance in liver and muscle while the adipose tissue remained insulin sensitive, though showing an increase in pathways facilitating fat accrual." (PMID 26946982, 2016). "The aim of the present manuscript was to establish and validate a technique to monitor the dynamics of insulin resistance in the pancreatic β-cell in vivo in the context of overall body insulin resistance and glucose homeostasis during the progression of T2DM in real-time." (PMID 26899548, 2016). "Several hypotheses were presented to confirm the higher prevalence of H. pylori infection in diabetic patients such as insulin resistance and abnormal insulin secretion were central to the development of T2DM." (PMID 27148410, 2016). "An interesting finding is that high-fish oil diet despite to any effect on glycaemia in confront of LD, it is able to attenuate the development of insulin resistance, preventing the alteration of glucose tolerance related to an impairment of insulin signalling due to fat over nutrition." (PMID 26901315, 2016). "Furthermore, we found a clear positive association between WL and the improvement of parameters for insulin resistance, insulin sensitivity and liver fat percentage in both groups." (PMID 27003699, 2016). "The primary aim of the present study was to determine which elements among the major terpenoids (betulin, betulinic acid, and oleanolic acid) in the extracts were most prominent and aided in the attenuation of insulin resistance and the potentiation of insulin secretion and cell proliferation." (PMID 26884795, 2016). "Future studies should measure insulin resistance to elucidate the impact that insulin and its downstream targets may play in cardiac remodeling in obese children." (PMID 27165194, 2016). "Insulin resistance is characterized by attenuation of the insulin effect." (PMID 27247938, 2016). "These phenomena might contribute to the compensatory insulin secretion seen during increased insulin resistance in aged mice." (PMID 27441644, 2016). "The case presents a patient who had extremely high endogenous insulin secretion but remained hyperglycemic (glucose levels 16.7–27.8 mmol/l) even on intravenous insulin (either regular or aspart) doses as high as 18,000 U/day, thus she had severe insulin resistance." (PMID 27142369, 2016). "BCAA supplementation also reduced the risk for HCC in obese patients with liver cirrhosis, which demonstrates the clinical significance of lowering insulin levels and attenuating insulin resistance in the prevention of liver carcinogenesis in obese and diabetic patients." (PMID 26871288, 2016). "Finally, patients with severe insulin resistance seemed the most sensitive to insulin concentration changes." (PMID 26819233, 2016). "In addition, lipids have an incretin effect, and a diet high in saturated fats determines insulin resistance and a higher glucose-stimulated insulin secretion (GSIS)." (PMID 27973438, 2016). "This upregulation of ANGPTL8 expression by insulin resistance was hypothesized to be a mechanism to increase insulin production through increasing β-cell proliferation." (PMID 27672665, 2016). "And elevated circulating irisin improves insulin resistance indirectly through lowering fasting insulin, although the underlying mechanisms are not yet fully understood." (PMID 27473122, 2016).
Insulin resistance (continued). "The hepatic insulin resistance derived from NAFLD generally implies the insufficient ability of insulin to suppress glycogenolysis, gluconeogenesis, and glucose output in the liver, thereby causing decreases in glucose disposal, consequently leading to type 2 diabetes (T2DM), and metabolic syndrome." (PMID 28036389, 2016). "In the study, using the supplement product could not significantly affect FPG and HbA1c but prevented the rise in serum insulin concentration and increase in insulin resistance." (PMID 27429803, 2016). "Authors concluded that insulin resistance could be a result of insulin's actions both in glucose uptake and hemodynamic regulation, highlighting the in vivo role of insulin as an endocrine regulator of cardiovascular physiology." (PMID 27014078, 2016). "Under oxidative stress conditions the insulin signaling is reduced, which may contribute to insulin resistance, and to the progression of diabetes and related complications." (PMID 27622707, 2016). "However, before hyperglycemia become overt enhanced pancreatic insulin secretion physiologically adapts to progressing insulin resistance in order to maintain euglycemic conditions as long as possible." (PMID 27505055, 2016). "It appears reasonable to assume that insulin-sensitizers drugs, by reducing the carcinogenic effects of obesity and insulin resistance, might be employed for long-term chemoprevention in women at high risk of endometrial cancer." (PMID 27725832, 2016). "Treatment of subjects with insulin resistance is directed at increasing insulin sensitivity." (PMID 26916435, 2016). "Interestingly, myopathic RAmKO and TSCmKO mice develop insulin resistance and show lower plasma glucose and plasma insulin concentrations." (PMID 27004103, 2016). "By using structural equation modeling, we found that elevated circulating irisin levels improve insulin resistance indirectly through lowering fasting insulin, which may be helpful to elucidate the mechanisms of insulin resistance." (PMID 27473122, 2016). "An example of this provided by this present study is insulin resistance, as the hypoglycaemic status of Tc1 mice indicates that chromosome 21 genes unique to this DS mouse model may improve some aspects of insulin sensitivity." (PMID 27195491, 2016). "Clinically, insulin resistance is characterized by reduced systemic insulin‐response." (PMID 27047746, 2016). "Among the blood components, total cholesterol (TC), high-density lipoprotein cholesterol, low-density lipoprotein cholesterol (LDLC), insulin and homeostatic model assessment-insulin resistance (HOMA-IR) were significantly different in the DE group compared to the HF group (p < 0.05)." (PMID 27596982, 2016). "Therefore, this study aimed to evaluate the change in Lp-PLA2 and sPLA2 levels after intensive insulin treatment and the correlation of these two enzymes with insulin resistance and pancreatic β-cell function in patients with newly diagnosed T2DM." (PMID 27881128, 2016). "The primary findings are: i) insulin resistance (P < 0.001) and hyperinsulinemia (P < 0.001); ii) decreased insulin disposal (P < 0.001); iii) trend for reduced GLP-1 responses at 75 g glucose; and iv) increased fasting glucagon levels (P < 0.001) in obese subjects." (PMID 26942445, 2016). "However, evidence, from obese humans that are developing insulin resistance, shows that insulin secretion can increase according to the demand." (PMID 27048248, 2016). "The rapid transit of undigested nutrients to the distal intestines upregulates the production of glucagon-like peptide 1 (GLP-1) and peptide-YY; moreover, GLP-1 can stimulate insulin secretion and antagonizes β-cell apoptosis, whereas peptide-YY can reduce insulin resistance." (PMID 27893867, 2016). "Finally, glycaemia, insulin and insulin resistance index (HOMA-IR index) were similar between the two groups." (PMID 26979133, 2016).
Insulin resistance (continued). "Treatment with adropin could reduce blood glucose levels and insulin resistance and improve insulin sensitivity in a rat model of T2DM." (PMID 27546995, 2016). "In addition to hyperglycemia and hyperlipidemia, insulin resistance, which is calculated according to the overall levels of blood glucose and serum insulin, is also a pivotal symptom in NAFLD." (PMID 27189109, 2016). "Besides, it has been reported that gene polymorphism is linked with PCOS (at least partially) through the role of this gene on insulin blood levels and insulin resistance (Mahmoudi, 2009)." (PMID 28096785, 2016). "These ethnic differences in fasting insulin and insulin resistance were appreciably reduced by adjustment for plasma vitamin C in all ethnic groups; the effects were particularly marked in Pakistani and Bangladeshi children, in whom the differences were reduced by 21 and 23%, respectively." (PMID 26498636, 2016). "Besides, high sucrose supplementation is widely used for induction of whole body insulin resistance in rats, whereby high levels of plasma insulin was detected." (PMID 27708685, 2016). "However, recent reports have not been able to replicate the effects of LPS on obesity and insulin resistance, and instead suggest that the glucose-stimulated insulin secretion (GSIS) is enhanced by LPS via the GLP-1 pathway." (PMID 26751381, 2016). "Moreover, the expression of this miRNA has been found to be abnormally elevated in islets and insulin target tissues of obese animals, contributing to beta cell failure and insulin resistance." (PMID 26474776, 2016). "Metformin may have improved outcome by improving insulin resistance, leading to lower levels of circulating insulin." (PMID 26967162, 2016). "High uric acid concentration may also impair normal endothelial function and may contribute to the development of hypertension or to that of insulin resistance by preventing insulin-induced vasodilation." (PMID 27125390, 2016). "The Sirt3 activator Oroxylin A and the histone acetyltransferase inhibitor CPTH2 obliterated (p < 0.05 vs. high insulin group) or overtly dampened insulin resistance-induced cardiomyocyte dysfunction and mitochondrial injury (aconitase activity) without eliciting any effects themselves." (PMID 27634872, 2016). "As PKC activation is associated with insulin resistance and obesity, PKC may underlie the reduced AMPK activity reported in response to overnutrition in insulin-resistant metabolic and vascular tissues." (PMID 27784766, 2016). "Moreover, there are many surrogate indices using glucose and insulin levels suggested as alternative measures of insulin resistance." (PMID 26752053, 2016). "Our models are kept as simple as possible by neglecting another feature present in the early onset of insulin resistance: namely, that the pancreas will supply higher levels of insulin to counterbalance small and moderate levels of insulin resistance in other tissues." (PMID 27306890, 2016). "LPL has been considered as a link between insulin resistance and atherosclerosis, given its role in controlling the delivery of free fatty acids to muscle, adipose tissue and vascular wall macrophages, wherein lipid uptake influences insulin sensitivity." (PMID 26999119, 2016). "However, despite the importance of macrophages in obesity and insulin resistance, the role of macrophage autophagy in regulating insulin sensitivity and glucose homeostasis is rarely addressed." (PMID 27229537, 2016). "Moreover, anti‐inflammatory adipokines such as insulin sensitizer adiponectin are decreased by excess weight gain and this decrease promotes insulin resistance in mice and humans." (PMID 26990883, 2016). "Future interactome studies of other signaling molecules along the canonical insulin signaling pathways might improve our understanding of insulin signaling and insulin resistance in skeletal muscle." (PMID 28248217, 2016).
Insulin resistance (continued). "Type 2 diabetes is a progressive and chronic disease characterized by both β-cell dysfunction and increased insulin resistance, defined as the inadequate response of skeletal muscle, liver, and adipose tissue to endogenous insulin secretions, and few drugs ameliorate increases in insulin resistance." (PMID 27413370, 2016). "This excessive level of fatty acids (associated with the Thr54) and their preferential use as a source of energy by skeletal muscle rather than glucose, contribute to an increase in glucose levels, higher basal and glucose-stimulated insulin levels and higher degree of insulin resistance." (PMID 27684940, 2016). "However, obese women have higher insulin resistance (lower insulin sensitivity) than women of normal weight, which results in elevated availability of lipids for fetal growth and development." (PMID 26758575, 2016). "Moreover, when further analyses in the subgroup of participants with data on insulin level (n = 711) that included insulin resistance (HOMA-IR in 90th) as a fifth metabolic abnormality." (PMID 27271659, 2016). "The uncontrolled hypertrophy of adipose tissue is characterized by the infiltration of macrophages, prominent source of proinflammatory cytokines, such as TNF-α and IL-6, that can block insulin signaling in adipocytes, providing a potential link between inflammation and insulin resistance." (PMID 26904104, 2016). "It further supports impaired insulin secretion and insulin resistance may involve in the pathogenesis of GDM as in T2D." (PMID 27468700, 2016). "Similarly, insulin resistance was reduced after 4 weeks of treatment in this study and insulin secretion was improved from 12 weeks." (PMID 26767080, 2016). "However, the recent finding of insulin resistance in T1D patients has driven attention to their use as adjunctive agents to insulin therapy." (PMID 27366200, 2016). "In line with the notion that an increase in fasting insulin (FI) indicates impairment of insulin signaling, we found that the homeostasis model assessment-estimated insulin resistance (HOMA-IR) index increased from 2.1 in the lean group to 6.0 in the overweight and obese group (p < 0.05)." (PMID 27298712, 2016). "HOMA-IR is a simple but effective measure of insulin resistance in fasting steady state conditions while ISI is a more complex estimation of insulin sensitivity incorporating glucose and insulin levels at the beginning (0 min) and end (120 min) of OGTT and body weight." (PMID 27736893, 2016). "A study demonstrating the anti-inflammatory properties of n-3 PUFA via suppression of toll-like receptor 4 (TLR4) activation in muscle reported improvements in inflammatory markers (TNFα, CRP, IL-6) and insulin resistance as measured from oral glucose and insulin tolerance tests (OGTT and ITT)." (PMID 27258299, 2016). "In addition, IL-6 induces the downstream NF-κB signaling pathway which impairs insulin signaling and subsequently induces insulin resistance in insulin-dependent tissues of obese humans and animals." (PMID 27069930, 2016). "Leptin stimulates insulin resistance whereas adiponectin elevates insulin sensitivity." (PMID 27122001, 2016). "HCL is an independent risk factor for insulin resistance and may be used to evaluate the risk of developing T2DM as a noninvasive marker of insulin sensitivity index." (PMID 27882331, 2016). "Adiponectin increases insulin sensitivity, whereas resistin increases insulin resistance." (PMID 27651836, 2016). "It has been suggested that fasting plasma insulin levels >15 mU/L could be a reasonable clinical alternative for evaluating insulin resistance." (PMID 27069678, 2016). "The effects of Delphinol presented here shall be of particular interest for individuals with glucose intolerance and insulin resistance, as pancreatic β-cells may be less burdened by excess insulin secretion." (PMID 28025651, 2016). "High insulin levels resulting from an insulin resistance lead to blood lipid abnormalities." (PMID 27101976, 2016).